CTSB (cathepsin B)
Diseases named in the same sentence as CTSB in open-access papers (continued):
Sharing a sentence is not in itself a finding about the gene and the disease.
endometrial cancer (5 papers, 2014 to 2024). Primary or metastatic malignant neoplasm involving the endometrium (mucous membrane that lines the endometrial cavity). "The mRNA expression of CTSB in cancer cell lines also indicated the thyroid and endometrial cancer had a relatively high CTSB expression." (PMID 35155389, 2022). "It was found that the expressions of CTSB in thyroid and gynecological cancer (especially endometrial cancer) were generally higher than any other cancer types in the two HPA data sets (HPA018156 and HPA048998) and TCGA data set." (PMID 35155389, 2022). "In a previous study enrolling 27 patients of endometrial cancer, increased expression of cathepsin B was found as a predictor of more aggressive cancer behavior over time, suggesting its potential as being a tumor marker of unfavorable outcome." (PMID 31692912, 2019). "We finally aimed to test whether also E2-BSA- mediated Ca2+ controls lysosomal activity in endometrial cancer cells, the result was verified by Western blot, Cathepsin B (CTSB) was expressed in the lysosomal fraction of Ishikawa cells, E2-BSA treatment caused the CTSB to enter the cytoplasm." (PMID 35223931, 2022).
heart failure (5 papers, 2018 to 2025). Inability of the heart to pump blood at an adequate rate to meet tissue metabolic requirements. "Therefore, CTSB is also considered a potential therapeutic target for heart failure." (PMID 40950552, 2025).
HIV-1 infection (5 papers, 2011 to 2025). The type species of lentivirus and the etiologic agent of acquired immunodeficiency syndrome (AIDS). "Conversely, high cathepsin B activity in the endosome was found to reversely correlate with the susceptibility to the mNDK strain, suggesting that in CD4-independent HIV-1 infection, cathepsin B in the endosome functions as a host defense factor." (PMID 40135892, 2025). "For example, cathepsin B inhibition by cystatin C or CA-074Me (synthetic inhibitor) treatment resulted in enhancement of the CD4-independent HIV-1 infection in HeLa and TE671 cells." (PMID 31077130, 2019). "Harman and colleagues have demonstrated that mRNA and protein expression of cathepsin B, C, S, and Z were profoundly decreased in human monocyte-derived DCs (MDDCs) after 48 h of HIV-1 infection." (PMID 31077130, 2019). "To visualize cathepsin B within lysosomes before and after HIV-1 infection, we performed double-immunofluorescence studies of cathepsin B and the lysosomal-associated membrane protein 2 (LAMP2) by in situ PLA co-localization assay." (PMID 22693552, 2012). "Our results demonstrate that HIV-1 infection upregulates cathepsin B in macrophages, increases cathepsin B activity, and reduces cystatin-cathepsin interactions, contributing to neuronal apoptosis." (PMID 22693552, 2012). "In this study, we showed that MDM released active cathepsin B and that HIV-1 infection increased levels of active cathepsin B over time of infection." (PMID 22693552, 2012). "Our results demonstrated that cathepsin B disappears from lysosomes after HIV-1 infection, suggesting its release from the organelle." (PMID 22693552, 2012). "To further understand the role of cathepsin B inhibitors in cathepsin B secretion and neurotoxicity after HIV-1 infection, we analyzed the protein-protein interactions between cathepsin B and cystatins B and C by in situ PLA." (PMID 22693552, 2012). "How HIV-1 infection of macrophages affects interactions between cathepsin B and its inhibitors, cystatins B and C, and thereby potentially impact neuronal survival was assessed in the current study." (PMID 22693552, 2012). "Our results provide evidence for the first time of a role for MDM-secreted cathepsin B in the neuronal apoptosis induced by HIV-1 infection." (PMID 22693552, 2012). "Our results demonstrate that HIV-1 infection of MDM leads to increased cathepsin B RNA levels, and increased cathepsin B secretion, activity, and neurotoxicity." (PMID 22693552, 2012). "The effect of HIV-1 infection on MDM expression of cathepsin B and its inhibitors, cystatin B and cystatin C, was assessed by Western blot and densitometry analysis." (PMID 22693552, 2012). "The target cells expressing higher level of cathepsin B activity were less susceptible to the CD4-independent mNDK vector infection, suggesting that cathepsin B inhibits the CD4-independent HIV-1 infection." (PMID 21541353, 2011). "We hypothesized that HIV-1 infection induces the release of cathepsin B from the lysosome to the cytosol and subsequently to the extracellular space." (PMID 22693552, 2012). "We hypothesized that HIV-1 infection induces the release of cathepsin B from lysosomes to the cytoplasm and the extracellular medium." (PMID 22693552, 2012). "Our study sought to determine whether HIV-1 infection could impact the interplay between cathepsin B and its inhibitors in macrophages." (PMID 22693552, 2012). "Under normal conditions, cathepsin B is located inside lysosomes, but oxidative stress induced by HIV-1 infection could stimulate the release of cathepsin B from this cellular compartment." (PMID 22693552, 2012). "This study indicates that cathepsin B inhibits CD4-independent HIV-1 infection." (PMID 21541353, 2011).
HIV-1 infection (continued). "This sequestration of cystatin B to the membrane limits the availability of this protein in the cytoplasm to inhibit released cathepsin B. Thus, multiple alterations in macrophage physiology induced by HIV-1 infection may act together to affect cathepsin B availability and activity." (PMID 22693552, 2012). "Thus, cathepsin B disappeared from lysosomes after HIV-1 infection." (PMID 22693552, 2012). "The mechanism by which cathepsin B inhibits the CD4-independent infection is suggested as follows; higher cathepsin B protease activity in SAOS-2, HeLa, and TE671 cells causes degradation of the HIV-1 particles in acidic endosomes, attenuating the CD4-independent HIV-1 infection." (PMID 21541353, 2011). "To determine whether cathepsin B might play a role in the neuronal injury induced by HIV, we first studied the effect of HIV-1 infection on gene and protein expression." (PMID 22693552, 2012). "Although HIV-1 infection did not affect intracellular cathepsin B levels per se, it increased the enzyme’s secretion and activity in HIV-infected MDM relative to uninfected control cells at 3 and 12 dpi." (PMID 22693552, 2012). "An important goal of our study was to determine if cathepsin B could have a potential role in HIV neuropathogenesis by analyzing its intracellular and extracellular expression and activity in MDM relative to HIV-1 infection." (PMID 22693552, 2012).
inflammatory bowel disease (5 papers, 2020 to 2025). A spectrum of small and large bowel inflammatory diseases of unknown etiology. "According to recent studies, CTSB levels in human fluids (serum or plasma) can be measured and remain within the diagnostic window after the onset of the inflammatory bowel diseases (IBD) including Crohn’s disease and Ulcerative colitis, enabling a non-invasive early detection of these diseases." (PMID 36944950, 2023). "Cathepsin B, a cysteine protease, is considered a potential biomarker for early diagnosis of cancer and inflammatory bowel diseases." (PMID 36944950, 2023).
ischemia (5 papers, 2015 to 2025). A hypoperfusion of the BLOOD through an organ or tissue caused by a PATHOLOGIC CONSTRICTION or obstruction of its BLOOD VESSELS, or an absence of BLOOD CIRCULATION. "Brain tissue loss was significantly prevented by cathepsin B inhibitor treatment of cerebral bleeding, ischemia, and kainic acid-induced Huntington’s chorea animal models." (PMID 26388830, 2015). "The cathepsin B protein levels were significantly higher in the I/R group than in the sham group at 24 h post-ischemia (P < 0.01)." (PMID 30046966, 2018). "For example, neuromotor, neurological learning and cognitive defects were improved by cathepsin B inhibition in cerebral bleeding, ischemia, epilepsy, and AD neurodegeneration animal models." (PMID 26388830, 2015). "Cathepsin B inhibitors have also been shown to prevent the vast majority of the neuronal cell death that occurs in ischemia and a great deal of the death resulting from cerebral bleeding animal models." (PMID 26388830, 2015). "Increased cathepsin B expression has long been known to result from ischemia with brain activity increasing about two- and fivefold relative to controls at 2 and 5 days after injury in ischemic rat and monkey models, respectively." (PMID 26388830, 2015). "The activation of cathepsin B and L led to a maximal increase in tBid, cytoplastic Cyt-c and active caspase-3, and conversely, a maximal reduction in mitochondrial Cyt-c during 12–24 h post-ischemia period." (PMID 28206988, 2017). "We found that, at the early stage of ischemia, OPN expression was enhanced, especially in microglia, and colocalized with LAMP1 and GAL-3, which was accompanied by lysosomal damage, CTSB release, NLRP3 inflammasome activation, and autophagosomes accumulation after HI insult." (PMID 36980197, 2023). "Moreover, deleting or inhibiting cathepsin B improves outcomes in injury models related to TBI including epilepsy, aneurysm, ischemia, pain, surgical trauma, spinal cord trauma, infectious disease, and neurodegeneration." (PMID 26388830, 2015).
liver cancer (5 papers, 2021 to 2025). An epithelial or non-epithelial malignant neoplasm that arises from the liver. "One such study using magnetic systems and iron oxide NPs on liver cancer cells found increased cathepsin B activity, supporting lysosomal membrane permeabilization and apoptosis induction." (PMID 40718436, 2025). "A previous study reported that cathepsin B plays a key role in hepatocellular apoptosis and liver injury and mediates liver cancer cell apoptosis contributing to inflammation and fibrogenesis." (PMID 37280603, 2023). "It has also been found that in liver cancer, IGF-1 promotes the invasion and metastasis of liver cancer cells by inhibiting the degradation of cathepsin B." (PMID 34804946, 2021).
lung disease (5 papers, 2018 to 2025). "Lung disease in CF is known to have its onset early in life and the higher concentration of cathepsin B is a potential indication of early airway damage." (PMID 29310632, 2018). "Through the comparison to healthy controls and older subjects with CF, our findings suggest that CCSP and cathepsin B are potential biomarkers of lung disease activity in infants and should be investigated in future longitudinal and mechanistic studies." (PMID 29310632, 2018). "Cathepsin B and Cystatin A expression at PAJs are thus a therapeutic vulnerability that could be exploited to prevent or even cure lung disease." (PMID 39747171, 2025). "Three biomarkers – desmosine, club cell secretory protein (CCSP) and cathepsin B have previously been associated with CF lung disease; however, their applicability to CF infants has not been investigated." (PMID 29310632, 2018). "In addition, the CF infants had significantly lower concentrations of cathepsin B in their urine and BALF compared to an older cohort of subjects with CF who had more established lung disease." (PMID 29310632, 2018).
metastatic cancer (5 papers, 2015 to 2025). A carcinoma which has spread from the original site of growth to another anatomic site. "Cathepsin B is a cysteine protease whose massive expression has been reported in several invasive and metastatic cancers." (PMID 36579638, 2023). "Targeting paxillin phosphorylation and cathepsin B/D could represent a promising approach for the treatment of metastatic cancer." (PMID 40861820, 2025). "Cathepsin B (CTSB) expression was significantly reduced in both primary cancer tissue and metastatic cancer tissue when compared to non-malignant prostate tissue (P ≤ 0.01)." (PMID 26473288, 2015).
multiple sclerosis (5 papers, 2014 to 2024). A progressive autoimmune disorder affecting the central nervous system resulting in demyelination. "However, we also identified traits with less clear connections to JIA, including platelet-to-lymphocyte ratio, sphingomyelin levels, cathepsin B levels, LILRB2 protein levels, multiple sclerosis, and giant cell arteritis." (PMID 39175752, 2024). "This study demonstrates the functional redundancy between cathepsin B, S and L in EAE, and suggests that the inhibition of multiple cysteine cathepsins may be needed to modulate autoimmune disorders such as multiple sclerosis." (PMID 26075905, 2015). "Moreover, microglia-derived cathepsin B, a target protein of CSTB, has been shown to have a role in WM damage in a mouse model of multiple sclerosis." (PMID 24603771, 2014).
myocardial infarction (5 papers, 2018 to 2025). Gross necrosis of the myocardium, as a result of interruption of the blood supply to the area, as in coronary thrombosis. "The cathepsin B-specific inhibitor Ca-074 Me significantly attenuated myocardial infarction caused by I/R in vivo and reduced hypoxia-induced cardiomyocyte apoptosis in vitro." (PMID 41323645, 2025). "CTSB may also be involved in the degradation of myogenic fibronectin in myocardial infarction." (PMID 37576397, 2023).
osteosarcoma (5 papers, 2019 to 2023). A usually aggressive malignant bone-forming mesenchymal neoplasm, predominantly affecting adolescents and young adults. "Cathepsin B, which plays a role in neoplastic invasiveness and neovascularization, can be activated by NF-kB in osteosarcoma." (PMID 34685761, 2021). "Thus, we further analyzed the LMP stability in DHA treated osteosarcoma cells using Acridine orange (AO) staining and measurement of the release of cathepsin B into the cytosol as described in earlier studies." (PMID 32431605, 2020). "This study demonstrates that H3NT proteolysis occurs in a cell density dependent manner in U2OS osteosarcoma cells, by the primary protease MMP-2 and the secondary and novel protease CTSB." (PMID 37161413, 2023).
sparganosis (5 papers, 2013 to 2022). A condition resulting from infection with the second stage larvae of the parasite Spirometra. "EgAg5 and cathepsin B also demonstrated cross-reactions with sera from neurocysticercosis and sparganosis." (PMID 25566682, 2015).
age-related macular degeneration (4 papers, 2019 to 2021). Age-related loss of vision in the central portion of the retina (macula), secondary to retinal degeneration. "In age-related macular degeneration (AMD), several examples of activators of the NLRP3 inflammasome have been identified, e.g., drusen and lipofuscin components, cathepsin B leaking from damaged lysosomes, and oxidative stress." (PMID 34062977, 2021).
amyotrophic lateral sclerosis (4 papers, 2011 to 2024). Amyotrophic lateral sclerosis (ALS) is a neurodegenerative disease characterized by progressive muscular paralysis reflecting degeneration of motor neurons in the primary motor cortex, corticospinal tracts, brainstem and spinal cord. "While cathepsin B of microglial origin has been shown to serve as an initiator of apoptosis in cultures of hippocampal and cortical neurons, its absence has been associated with the death of motor neurons in amyotrophic lateral sclerosis." (PMID 21794126, 2011).
aneurysm (4 papers, 2013 to 2022). Bulging or ballooning in an area of an artery secondary to arterial wall weakening. "Due to the multi-step, stringent filtration process chosen for this proteomics dataset, there are proteins ultimately listed as associated with only one AAA model (e.g., CORO1A in AngII, and CTSB in elastase), which are in actuality increased in the respective aneurysm region for both models." (PMID 35990960, 2022). "Similarly, in an aneurysm model, cathepsin B mRNA increased about fivefold and activity increased about twofold 3 months after aneurysm induction relative to controls." (PMID 26388830, 2015).
Anxiety (4 papers, 2011 to 2025). Intense feelings of nervousness, tension, or panic often arise in response to interpersonal stresses. "Transcriptome analysis of inbred mouse lines selected for high or low anxiety-related behaviors revealed that CTSB is associated with reduced anxiety in female mice." (PMID 41463031, 2025). "In contrast, cathepsin B induces neuroinflammation by activated microglia and protects against anxiety- and depressive-like behaviours." (PMID 37958596, 2023). "This suggests that CTSB may enhance neuronal resilience and plasticity, thereby mitigating anxiety and depressive symptoms." (PMID 41463031, 2025).
cardiac hypertrophy (4 papers, 2015 to 2026). "With relevance to cardiac aging, cathepsin B has been shown to directly affect cardiac hypertrophy and fibrosis, both of which increase in human and animal studies of cardiac ageing." (PMID 40915658, 2025). "In a mice model of CVB3-induced viral myocarditis and pressure overload-induced cardiac hypertrophy, CTSB was upregulated in cardiomyocytes and promoted cardiac inflammation and dysfunction through activating the inflammasome or TNF-α/ASK1/JNK apoptotic signaling pathway." (PMID 41277866, 2026). "In this study, CTSB and CTSL were found to be downregulated in cardiac hypertrophy, potentially implying slightly limited myocardial proteolytic activity." (PMID 32176724, 2020). "CTSB is upregulated in cardiomyocytes and stimulates the aortic banding-induced activation of TNF-α and cytochrome c release, thereby enhancing pressure overload-induced cardiac hypertrophy and fibrosis." (PMID 41277866, 2026).
emphysema (4 papers, 2016 to 2023). "Increased MMP9, CD147 and cathepsin B levels in ATII cells in emphysema may suggest their contribution to alveolar wall destruction." (PMID 29476075, 2018). "We also checked MMP9, CD147 and cathepsin B mRNA levels by RT-PCR in lung tissue obtained from control non-smokers, smokers and patients with emphysema." (PMID 29476075, 2018). "Our results suggest that cathepsin B may contribute to ATII cell injury under high oxidative stress induced by CS and in emphysema as well." (PMID 29476075, 2018). "Considering the role of MMP9, CD147 and cathepsin B in COPD development, we wanted to check their intracellular levels in ATII cells and lung tissue obtained from patients with emphysema compared to control non-smokers and smokers." (PMID 29476075, 2018).
epilepsy (4 papers, 2014 to 2019). A brain disorder characterized by episodes of abnormally increased neuronal discharge resulting in transient episodes of sensory or motor neurological dysfunction, or psychic dysfunction. "TBI causes excitotoxicity and cathepsin B protein levels are elevated in excitotoxicity animal models of recurring epilepsy and Huntington’s chorea." (PMID 26388830, 2015). "CTSB gene knockout experiments showed that CTSB was involved in epilepsy-related apoptotic cell death." (PMID 29068414, 2017). "In epilepsy animal models, seizures result in translocation of lysosomal cathepsin B to the cell body and nucleus." (PMID 26388830, 2015). "Alterations in CTSB expression have been found at various diseases, including epilepsy and cancer." (PMID 24452274, 2014). "Deleting the cathepsin B gene produces significant beneficial outcomes in TBI-related pathological animal models and includes surgery, epilepsy, AD, inflammation, pain, and cytokine cell death models." (PMID 26388830, 2015).